TAC1 (tachykinin precursor 1)
Diseases named in the same sentence as TAC1 in open-access papers (continued):
Sharing a sentence is not in itself a finding about the gene and the disease.
Stroke (19 papers, 2013 to 2025). Sudden impairment of blood flow to a part of the brain due to occlusion or rupture of an artery to the brain. "Tac1 encodes endogenous substance P, which can reportedly prevent the delayed degeneration of dopaminergic neurons after stroke." (PMID 39273659, 2024).
colitis (17 papers, 2014 to 2025). Inflammation of the colon. "Moreover, another study of UC (GSE47908) revealed that TAC1 expression was significantly higher in patients with pancolitis than in those with left-sided colitis and normal individuals, whereas TRPM8 showed the opposite trend." (PMID 38280896, 2024). "Our study found that TRPM8, TAC1 and WNT3A expression were significantly correlated with the severity of ulcerative colitis in patients and DSS-induced colitis in mice." (PMID 38280896, 2024). "The results showed that Trpm8 and Tac1 expression were significantly decreased and increased, respectively in the DSS-induced colitis group." (PMID 38280896, 2024).
neuropathy (15 papers, 2009 to 2025). A disorder affecting the nervous system that manifests with pain, tingling, numbness, and/or muscle weakness. "A GWAS on oxaliplatin-induced neuropathy implicated genes relating to nerve development and neuron extension (FOXC1 and ITGA1) and pain signaling neurotransmitters (TAC1)." (PMID 30909387, 2019).
Sepsis (15 papers, 2010 to 2024). Sepsis is defined as life-threatening organ dysfunction caused by a dysregulated host response to infection. "Substance P (SP), encoded by the TAC1/Tac1 gene, acts as a significant mediator in dysregulated systemic inflammatory response and associated organ injury in sepsis by activating the neurokinin-1 receptor (NK1R)." (PMID 38539834, 2024). "In a CLP sepsis model, it was found that in mice deficient in the SP gene (Tac1), the liver sinusoidal damage caused by sepsis was reduced, highlighting the potential harmful effects of SP on liver injury." (PMID 39769181, 2024). "Substance P (SP), encoded by the Tac1 gene, has been shown to promote leukocyte infiltration and organ impairment in mice with sepsis." (PMID 38928206, 2024). "In contrast to the changes in the concentration of iron and MDA found in the liver and lungs, Tac1+/+ mice with CLP-surgery-induced sepsis showed lower concentrations of GSH in the liver (p < 0.001) and lungs (p < 0.001) than the sham-operated controls." (PMID 38539834, 2024). "The concentration of MDA in the liver was significantly increased in the Tac1+/+ mice with CLP-surgery-induced sepsis compared with the sham-operated controls (p < 0.001)." (PMID 38539834, 2024). "The expression of NK1R in the liver (p < 0.001) and lungs (p < 0.001) was significantly elevated in the Tac1+/+ mice with CLP-surgery-induced sepsis compared with the sham-operated controls." (PMID 38539834, 2024). "The concentration of iron in the liver was significantly increased in the Tac1+/+ mice with CLP-surgery-induced sepsis compared with the sham-operated controls (both the Tac1+/+ mice and the Tac1−/− mice, p < 0.001)." (PMID 38539834, 2024). "We also found that NK1R antagonist treatment did not cause any further effect on the profile of ferroptosis as well as acute inflammatory response and injury in the liver and lungs in Tac1−/− mice with CLP-surgery-induced sepsis." (PMID 38539834, 2024). "The concentrations of IL-1β (p < 0.001), IL-6 (p < 0.001), and TNF-α (p < 0.001) were significantly elevated in the liver in the Tac1+/+ mice following CLP-surgery-induced sepsis compared with the sham-operated controls." (PMID 38539834, 2024). "The concentration of Nrf2 in the liver was significantly reduced in the Tac1+/+ mice with CLP-surgery-induced sepsis compared with the sham-operated controls (p < 0.001)." (PMID 38539834, 2024). "In addition, the deficiency of the Tac1 gene was linked to a lower level of systematic production of chemokines, recruitment of neutrophils, and bacterial burden, which underlies the detrimental effects of SP on lung inflammation and injury in sepsis, as well as the overall outcome of septic mice." (PMID 37047113, 2023). "Several manifestations of sepsis occurred in Tac1+/+ mice during the development of sepsis." (PMID 38539834, 2024). "Similarly, the expression of Gpx4 in the liver in the Tac1+/+ mice with CLP-surgery-induced sepsis was lower than in the sham-operated controls (p < 0.001)." (PMID 38539834, 2024). "The typical manifestations of sepsis, including piloerection, shivering, reduced vigilance and movement, lethargy, ocular and nasal discharge, lower food and water consumption, and faecal adhesions on the anus, were observed in the Tac1+/+ mice following CLP-surgery-induced sepsis." (PMID 38539834, 2024). "Notably, this study showed that these increases in the concentration of iron and MDA in the liver and lungs in mice following CLP-surgery-induced sepsis were reduced by either the deletion of the Tac1 gene, the pharmacological blockage of NK1R, or the combination of these two methods." (PMID 38539834, 2024). "More recently, it was reported that the deficiency of the Tac1 gene protected mice against sepsis-induced damage in the liver sinusoid, which may also underlie the detrimental impacts of SP on liver injury in CLP-induced sepsis." (PMID 37047113, 2023).
Sepsis (continued). "Moreover, following sepsis, mice lacking the Tac1 gene had a better prognosis than wildtype mice, as evidenced by the delayed onset of lethality and higher survival probability." (PMID 37047113, 2023). "Moreover, if the NK1R antagonist was utilized to block the actions of NK1R, the deletion of the Tac1 gene did not cause any further effect on the profile of ferroptosis as well as acute inflammatory response and injury in the liver and lungs in mice with CLP-surgery-induced sepsis." (PMID 38539834, 2024).
Arthritis (14 papers, 2009 to 2025). Inflammation of a joint. "At elevated levels in OA synovial fluid, NK1-receptor antagonists show analgesic efficacy in rodent models of arthritis, and TAC1 SNPs are associated with symptomatic knee OA pain." (PMID 40563469, 2025). "Although the patterns and levels of expression of Tac1- and Tac4-derived peptides at early time points prior to the immune response initiation is not known, the present results outline the complexity of the tachykinin system in different mechanisms in arthritis and arthritis-related pain." (PMID 23626716, 2013). "We examined mRNA expression levels of TRPA1, TAC-1 and CGRP from joint tissues in mice maintained at RT or exposed to cold, 2 weeks after arthritis induction, in order to detect the start of any potential changes caused by acute cold exposure." (PMID 26754745, 2016). "TAC1 was not correlated with the immune cell content in cluster B arthritis patients, and resting memory CD4 T cells and activated NK cells were not correlated with the gene signatures." (PMID 35734177, 2022).
Obesity (11 papers, 2021 to 2025). Accumulation of substantial excess body fat. "Among them, namely Tac1 encoding SP and NKA, Tac3 encoding NKB, and Tac4 encoding HK-1 or EKs, Tac1 encoding product SP plays an important role in a variety of physiological behaviors such as pain perception, neurogenic inflammation, smooth muscle contraction and obesity regulation." (PMID 38254396, 2024).
periodontitis (10 papers, 2013 to 2024). An acute or chronic inflammatory process that affects the tissues that surround and support the teeth. "To determine functional roles of SP and CGRP, encoded by Tac1 and Calca gene respectively, we used Tac1 and Calca knockout mice for ligature-induced periodontitis experiments." (PMID 37122730, 2023). "Interestingly, the deletion of tachykinin precursor 1, a gene that encodes SP, or the treatment of gingiva with an SP antagonist, significantly reduces bone loss in ligature-induced periodontitis." (PMID 38455874, 2024). "Altogether, these results indicate that Tac1 KO mice exhibit reduced host response in ligature-induced periodontitis and suggest that SP is a major neurogenic regulator of host immune responses and alveolar bone loss in periodontitis." (PMID 37122730, 2023). "Given that the regulation of host responses by neuropeptides underlies the neural regulation of barrier tissue functions, we further investigated the role of Tac1 in the recruitment of immune cells to sites of periodontitis." (PMID 37122730, 2023).
endometriosis (9 papers, 2014 to 2025). The growth of functional endometrial tissue in anatomic sites outside the uterine body. "The neuropeptide substance P (encoded by the TAC1 gene) has been immunolocalized to endometriosis lesions, and TRPA1 has been implicated in thermal and mechanical hypersensitivity to pain." (PMID 25029427, 2014). "TRPV1, SCN9A, and TAC1 were elevated in endometriosis lesions (P < .05)." (PMID 25029427, 2014).
osteoarthritis (9 papers, 2015 to 2026). A noninflammatory degenerative joint disease occurring chiefly in older persons, characterized by degeneration of the articular cartilage, hypertrophy of bone at the margins and changes in the synovial membrane. "This led to the identification of 411 differentially expressed genes (DEGs) related to osteoarthritis, 2485 DEGs among subgroups, as well as 238 intersecting genes and 5 hub genes (MMP13, FAM26F, CHI3L1, TAC1, and CKS2)." (PMID 40216809, 2025).
Parkinson disease (8 papers, 2015 to 2024). A progressive degenerative disorder of the central nervous system characterized by loss of dopamine producing neurons in the substantia nigra and the presence of Lewy bodies in the substantia nigra and locus coeruleus. "The DisGeNET database labels NLRP1, MSC, PTK2B, TAC1 and FOSL2 as genes associated with Parkinson’s disease, with association scores of 0.964, 0.944, 0.907, 0.889 and 0.888, respectively." (PMID 38350848, 2024).
pulpitis (8 papers, 2012 to 2025). Inflammation of the dental pulp. "During irreversible pulpitis, Piezo2 downregulation occurs despite its strong association with pain mediators (neuropeptide Y (NPY), substance P, Tachykinin 1 (TAC1)) and overall pain intensity." (PMID 40708698, 2025).
leukemia (7 papers, 2005 to 2024). A malignant (clonal) hematologic disorder, involving hematopoietic stem cells and characterized by the presence of primitive or atypical myeloid or lymphoid cells in the bone marrow and the blood. "A study in leukemia has demonstrated that collagen promotes doxorubicin resistance by reducing DNA damage through the inhibition of Tac1 activation." (PMID 39123364, 2024).
neuroblastoma (6 papers, 2017 to 2023). Neuroblastoma (NB) is the most common solid, extracranial childhood tumor. "TAC1 mRNA (which codes for SP and is the natural ligand of NK1R) expression levels were high in rhabdoid tumors and neuroblastoma, but not significantly different to the other tumors." (PMID 35049682, 2021).
schizophrenia (6 papers, 2012 to 2024). A major psychotic disorder characterized by abnormalities in the perception or expression of reality. "We found dysregulation of multiple transcripts whose human orthologs are associated with BPD and other psychiatric disorders including schizophrenia and ADHD, including: Epor, Smarca4, Cmklr1, Cat, Tac1, Npsr1, Fhit, and P2rx7." (PMID 22675514, 2012).
epilepsy (5 papers, 2016 to 2020). A brain disorder characterized by episodes of abnormally increased neuronal discharge resulting in transient episodes of sensory or motor neurological dysfunction, or psychic dysfunction. "Sst_Tac1/3 interneurons were among the subtypes most affected by epilepsy across GABAergic interneurons based on the metric that assessed changes in gene expression and cell-type composition." (PMID 33028830, 2020). "Thus, L2–3_Cux2 and L5–6_Fezf2 subtypes co-clustered with Sst_Tac1 and Vip_Cbln1 subtypes, whereas L3_Cux2_Prss12 co-clustered with Pvalb_Sulf1, which might underlie local neuronal networks with most strongly affected in the epilepsy transcriptome." (PMID 33028830, 2020).
pancreatic cancer (5 papers, 2016 to 2023). "TAC1 hypermethylation has been observed in several cancer types, including lung, colorectal, head and neck, uterine, and pancreatic cancer." (PMID 37176055, 2023). "Cell-free DNA hypermethylation of BMP3, MESTv2, SST, TFPI2, TAC1, ALX4, HIC1, SFRP2, SEPT9v2 and WNT5A has not previously been described in the literature in relation to pancreatic cancer." (PMID 27891190, 2016).
endometrial carcinoma (4 papers, 2018 to 2022). A malignant tumor arising from the epithelium that lines the cavity of the uterine body. "LOC134466/hsa-miR-196a-5p/TAC1 axis promotes cell proliferation of endometrial carcinoma." (PMID 32982585, 2020). "The decrease of LOC134466 and TAC1 expression in endometrium cancer suggested that the two gens may play a tumor-suppressive role in EC tumorigenesis." (PMID 30485833, 2018). "It regulates the axis LOC134466/hsa-miR-196a-5p/TAC1, which activates neuroactive ligand-receptor interactions by activating TACR3 in endometrial cancer (EC)." (PMID 36090902, 2022).
autism (3 papers, 2011 to 2019). Persistent deficits in social interaction and communication and interaction as well as a markedly restricted repertoire of activity and interest as well as repetitive patterns of behavior. "There is only one study in which the association between three SNPs of the TAC1 gene and autism has been searched." (PMID 31254375, 2019).
hepatoblastoma (3 papers, 2019 to 2024). Hepatoblastoma (HB) is a malignant hepatic tumor and is the most common pediatric liver cancer. "Similar to our recent study in hepatoblastoma, we here demonstrated for rhabdoid tumors that the expressions of TACR1 and TAC1 do not seem to correlate to parameters such as stage of disease, gender, and age of diagnosis." (PMID 35049682, 2021).
non-small cell lung carcinoma (3 papers, 2021 to 2024). A group of at least three distinct histological types of lung cancer, including non-small cell squamous cell carcinoma, adenocarcinoma, and large cell carcinoma. "High-frequency methylation profiles have been reported for several cancer-specific genes, including SOX17, TAC1, HOXA7, CDO1, HOXA9, and ZFP42, in both preoperative plasma and sputum samples from lymph node-negative stage I and IIA non-small cell lung cancer (NSCLC) patients." (PMID 37840147, 2023).
respiratory depression (3 papers, 2023 to 2025). A decrease in ventilation secondary to impaired signals from the central nervous system. "Photostimulation of tachykinin precursor 1 (Tac1) preBötzinger Complex (preBötC) cells reverses respiratory depression by the opioid fentanyl." (PMID 37458576, 2023). "We characterized a subpopulation of glutamatergic neurons expressing the Tac1 gene promoting breathing that can be targeted to reverse respiratory depression by opioid drugs." (PMID 37458576, 2023). "In our study, we found co-expression of Oprm1 (the gene coding for MORs) and Tac1 in preBötC neurons, and stimulation of Tac1 preBötC cells entirely reversed respiratory depression by fentanyl." (PMID 37458576, 2023). "Considering that photostimulation of Tac1 cells increased breathing and that these cells co-expressed Oprm1, we aimed to determine whether stimulation of Tac1-expressing cells can reverse opioid-induced respiratory depression." (PMID 37458576, 2023). "Consistent with this hypothesis, we showed that stimulation of Tac1 preBötC cells alleviated respiratory depression by fentanyl in intact animals." (PMID 37458576, 2023). "Considering the role of Tac1-expressing cells in rhythmic breathing and knowing that the preBötC plays a major part in respiratory depression by opioid drugs, we determined whether Tac1 mRNA is co-expressed with Oprm1 (gene for MORs) mRNA in the preBötC." (PMID 37458576, 2023). "In mice lacking the Tac1 gene, which encodes the peptide substance P, the endogenous ligand for neurokinin-1 receptors, morphine induced a reduced respiratory depression compared with wild-type mice." (PMID 37364996, 2023). "Moreover, an excitatory Tac1 spinal-brainstem circuit mediates noxious responses in rodents and deletion of the Tac1 gene in mice increases the inhibitory effects of opioid drugs, suggesting that substance P could reverse respiratory depression by opioid drugs." (PMID 37458576, 2023).
head and neck squamous cell carcinoma (2 papers, 2019 to 2024). A squamous cell carcinoma that arises from any of the following anatomic sites: lip and oral cavity, nasal cavity, paranasal sinuses, pharynx, larynx, and salivary glands. "The same phenomenon has been reported for methylated TAC1 promoter DNA for esophageal squamous cell carcinoma, SHOX2 and SEPT9 for head and neck squamous cell carcinomas." (PMID 30849971, 2019).
myeloma (2 papers, 2015 to 2025). "In addition, screening of multiple myeloma surface antigens has identified other promising targets, including CD28 (Tp44), CD48 (BLAST), CD74 (CLIP), CD138 (SDC1), CD229 (SLAMF3), CD319 (SLAMF7), CCR10 (GPR2), TAC1 (NPK), TXNDC11, SLC1A5 (AAAT)." (PMID 41369346, 2025).
narcolepsy (2 papers, 2018 to 2021). A sleep disorder characterized by a tendency for excessive sleepiness during the day which occurs even after adequate sleep in the nighttime. "Evidence indicates that TAC1 plays a main role in narcolepsy and the low level of this protein is recorded." (PMID 34466439, 2018).
oral cancer (2 papers, 2018). "TAC1 methylation in oral cancer was significantly associated with the OR for recurrence (OR = 4.427, 95% CI 1.634–12.00, P = 0.003)." (PMID 29682090, 2018). "In patients with oral cancer, TAC1 methylation showed the best correlation with poor survival (odds ratio 4.427, 95% CI 1.634–12.00, P = 0.003)." (PMID 29682090, 2018). "In patients with oral cancer, the methylation of TAC1 and SSTR1 best correlated with poor survival (hazard ratio: 4.29; p = 0.005 and 5.38; p = 0.029, respectively)." (PMID 29361757, 2018). "Moreover, to our knowledge, our study is the first to suggest that TAC1, HCRT, and GAL methylation is associated with worse DFS and that this may be a critical event in oral cancers, laryngeal cancers, and oropharyngeal cancers, respectively." (PMID 29682090, 2018).
Psychosis (2 papers, 2008 to 2016). "The genes down-regulated in psychosis include neuropeptide genes such as somatostatin (SST), neuropeptide Y (NPY) and tachykinin (TAC1)." (PMID 18992145, 2008). "Using a quantitative PCR, we validated a set of genes such as up-regulated metallothioneins (MT1E, MT1F, MT1H, MT1K, MT1X, MT2A and MT3) and down-regulated neuropeptides (SST, TAC1 and NPY) in the dorsolateral prefrontal cortex of psychosis patients." (PMID 18992145, 2008). "We have also confirmed that expression of the neuropeptide genes are down-regulated in psychosis; NPY (p = 0.02, FC -1.32), NR4A2 (p = 0.01, FC -1.39), SST (p = 0.001, FC -1.57) and TAC1 (p = 0.01, FC -1.6)." (PMID 18992145, 2008).
skin cancer (2 papers, 2019 to 2023). "The rabbit skin tumours induced via blood infection displayed decreased expression of SLN, TAC1, MYH8, PGAM2, and APOBEC2 and increased expression of SDRC7, KRT16, S100A9, IL36G, and FABP9, as seen in tumours induced by local infections." (PMID 31340720, 2019).
xerostomia (2 papers, 2018 to 2021). Dryness of the mouth resulting from reduced salivary secretion. "Moreover, significant correlations were observed between xerostomia and TAC1, TAC2, and CUPRAC, and between pain and drainage and TAC1, CUPRAC, and FRAP." (PMID 34356320, 2021). "When data of the two groups and the two samplings were pooled, significant correlations were observed between pain and drainage and TAC1, CUPRAC, and FRAP, and between xerostomia and the TAC1, TAC2, CUPRAC, and FRAP." (PMID 29992150, 2018). "Significant correlations were observed between pain and drainage and TAC1, CUPRAC, and FRAP and between xerostomia and the TAC1, TAC2, CUPRAC, and FRAP." (PMID 29992150, 2018).